ENSG00000251802
Gene: Small nucleolar RNA gene on chromosome 7 (34,892,417 to 34,892,549, forward strand). Ensembl gene ENSG00000251802.
Homologues: Orthologues: rat LOC120102627 (73% identical). Paralogues in human: SNORA31B (80% identical), SNORA31 (65% identical).